HMSD (histocompatibility minor serpin domain containing)
Description:
This splice variant of HMSD is the precursor of the histocompatibility antigen ACC-6. More generally, minor histocompatibility antigens (mHags) refer to immunogenic peptide which, when complexed with MHC, can generate an immune response after recognition by specific T-cells. The peptides are derived from polymorphic intracellular proteins, which are cleaved by normal pathways of antigen processing. The binding of these peptides to MHC class I or class II molecules and its expression on the cell surface can stimulate T-cell responses and thereby trigger graft rejection or graft-versus-host disease (GVHD) after hematopoietic stem cell transplantation from HLA-identical sibling donor. GVHD is a frequent complication after bone marrow transplantation (BMT), due to mismatch of minor histocompatibility antigen in HLA-matched sibling marrow transplants. However, associated with GVHD, a favorable graft-versus-leukemia (GVL) can be induced by donor-recipient disparities in mHags. ACC-6 is presented to the cell surface by MHC HLA-B*4403. This complex specifically elicits donor-cytotoxic T-lymphocyte (CTL) reactivity against hematologic malignancies after treatment by HLA-identical allogenic BMT. It induces cell recognition and lysis by CTL. Immunogenicity of most autosomal mHags results from single-nucleotide polymorphisms that cause amino-acid substitutions within epitopes, leading to the differential recognition of peptides between donor and recipient. Putative serine protease inhibitor.
Synonyms: HSMD-v; C18orf53; ACC-6; ACC6
Tractability: Antibody: its Gene Ontology location is reachable by antibodies, with medium confidence.
Gene: Protein-coding gene on chromosome 18 (63,949,301 to 63,981,774, forward strand). Ensembl gene ENSG00000221887.
Subcellular location: Secreted
Gene Ontology:
Molecular function: serine-type endopeptidase inhibitor activity
Biological process: activation of immune response
Cellular component: extracellular region
Genetic constraint (gnomAD): Loss-of-function variants: 12 observed, 7.3 expected, observed/expected ratio (o/e) 1.64, 90% interval 1 to 1.95. That is too few expected variants to judge how well the gene tolerates losing a copy. Missense variants: 130 observed, 142.69 expected, observed/expected ratio (o/e) 0.91, 90% interval 0.79 to 1.05. Synonymous variants: 46 observed, 48.69 expected, observed/expected ratio (o/e) 0.94, 90% interval 0.75 to 1.21.
Homologues: Orthologues: chimpanzee HMSD (94% identical). Paralogues in human: SERPINB8 (58% identical), SERPINB6 (55% identical), SERPINB9 (48% identical), SERPINB1 (39% identical), SERPINB4 (39% identical), SERPINB3 (38% identical), SERPINB2 (35% identical), SERPINB10 (34% identical), SERPINB13 (34% identical), SERPINB11 (32% identical), SERPINC1 (32% identical), SERPINA6 (31% identical), and 24 more.
Diseases named in the same sentence as HMSD in open-access papers:
HMSD is named in the same sentence as 1 disease in open-access papers, as found by Europe PMC text mining. Sharing a sentence is not in itself a finding about the gene and the disease. The quoted sentences say what the papers report.
plague (1 paper, 2023). Plague is a severe bacterial infection caused by the gram-negative bacterium Yersinia pestis. "Because HmsD is the predominant DGC in the flea, CsrA-dependent regulation of c-di-GMP levels through HmsD may serve as an important fine-tuning mechanism for the development of a transmissible Y. pestis infection from its flea vector and spread of plague by fleabite." (PMID 37191545, 2023).